BRAF (B-Raf proto-oncogene, serine/threonine kinase)
Diseases named in the same sentence as BRAF in open-access papers (continued):
Sharing a sentence is not in itself a finding about the gene and the disease.
tumor (continued). "Patients underwent a blood-sampling screening procedure to identify their RAS and BRAF tumor status." (PMID 34495337, 2021). "Grade 2–3 ST (HR, 0.51; CI 95%, 0.29–0.89; p = 0.019) and RAS/BRAF/EGFR WT circulating tumor DNA (ctDNA) (HR, 0.50; CI 95%, 0.27–0.9; p = 0.019) had a statistically significant effect on OS at univariate analysis." (PMID 34830870, 2021). "The tumor-bearing model of BRAF inhibitor was established using TE-1 cells, and corresponding negative control was set up to observe the growth rate of the two models." (PMID 33622273, 2021). "We showed that MEKi-mediated induction of melanosomal antigens, particularly TYRP1, combined with the administration of anti-tumor antibodies resulted in an enhanced therapeutic effect in both the BRAF-WT and BRAFV600E models." (PMID 33520112, 2021). "Subsequently, MMR-deficient CRCs are tested for BRAF c.1799T>A (p.V600E) variants and MLH1 promoter methylation to improve screening specificity, as both are associated with sporadic tumours (p < 0.001)." (PMID 33499123, 2021). "The combination of small molecule HDAC inhibitor Panobinostat and PCI-30451 significantly reduced tumor burden and enhances the sensitivity to BRAF inhibitors proving HDAC8 inhibitors as a promising role in therapeutics." (PMID 33670008, 2021). "Then, they showed that cetuximab-based BiTE antibody mediated potent redirected lysis of KRAS- and BRAF-mutated CRC lines in vitro and prevented the growth of tumours from xenografts." (PMID 34663410, 2021). "Combination BRAF-MEKi can shape the tumor microenvironment by reducing immunosuppressive factors such as vascular endothelial growth factor, IL-6, IL-10, and TGF-β which corresponds with increasing tumor infiltrating lymphocytes." (PMID 34944961, 2021). "Immunohistochemical (IHC) staining with anti-BRAF V600E antibody displayed strong positive staining in the tumor tissues." (PMID 34502061, 2021). "Snai2 was found to associate with the gender, histological variants, BRAF/RAS phenotype, and lymph node metastases, while Zeb1 was found to be associated significantly with the histological variants, BRAF phenotype, tumor size, and disease recurrences." (PMID 34575184, 2021). "As the role of targeted therapy for the treatment of metastatic CRC has become essential, the NCCN Panel recommends the determination of tumor gene status for KRAS/RAS and BRAF mutations, as well as HER2 amplifications." (PMID 34598716, 2021). "Given that a postoperative drop in BRAF (V600E) ctDNA levels was observed in all cases suggests its utility as a tumor marker." (PMID 34475951, 2021). "Our systems pharmacology approach highlights a path toward identifying actionable epigenetic factors that extend the BRAF oncogene addiction paradigm on the basis of tumor cell differentiation state." (PMID 33750776, 2021). "AZD0364 exhibited dose- and time-dependent modulation of ERK1/2-dependent signaling to result in tumor regression in sensitive BRAF-and KRAS-mutant xenografts." (PMID 34301278, 2021). "Consistent with other studies BRAF-MEK-CDK4/6i led to robust anti-tumor activity in both BRAFi resistant SM1WT1 and BRAFi sensitive YOVAL1.1 models and importantly did not adversely affect the response to ACT." (PMID 34944961, 2021). "Tumor-associated genes on Chr9q such as FANCC, NTRK2, SYK, and NOTCH1 were amplified; amplification of BRAF, EZH2, MET, CDK6 and HGF located on Chr7 were also detected." (PMID 34895266, 2021). "There is already emerging data that suggest that BRAF inhibitors are a potent radiation sensitizer, and low dose radiotherapy can enhance T cell infiltration within the tumor micro-environment." (PMID 33557890, 2021). "Some studies have observed a paradoxical activation of tumor growth with BRAF/MEK inhibitor treatment, especially in KIAA1549-BRAF- and NF-1-mutated pLGG." (PMID 34828788, 2021). "We also compared the anti-tumor effects of BRAF inhibitors sorafenib and vemurafenib in the canine TCC cell lines." (PMID 34502061, 2021).
tumor (continued). "The choice of treatment and patient selection was based on multidisciplinary tumor board evaluations where primary tumor sidedness, RAS and BRAF mutations, and MSI status were previously disregarded in decision making." (PMID 34440165, 2021). "In the combined RAS and BRAF wildtype cohort the majority of the tumours were left-sided (75%; COIN: 81% and PICCOLO: 69%)." (PMID 34253874, 2021). "To address this question, we isolated total RNA from FFPE (Formalin-Fixed Paraffin-Embedded) tumor samples before treatment with kinase inhibitors or from metastatic lesions after relapse in patients who developed resistance to BRAF inhibitors." (PMID 33670365, 2021). "The approach exploits a blood biopsy to detect circulating tumour DNA (ctDNA), which can be a simple way to test for MRD, based on assessment of BRAF, NRAS, or TERT mutations that are present in more than 75% of melanoma patients’ tumours." (PMID 36284898, 2021). "Emergent tumours in this model recapitulate the topography, molecular landscape, and metastatic tropism of human right-sided disease, lending important insights into the pathogenesis of mutant BRAF-driven rCRCs that arise via the serrated neoplasia pathway." (PMID 34103493, 2021). "Tumor shrinkage is the main consideration when selecting treatment options for RAS/BRAF WT cytoreduction patients." (PMID 34868987, 2021). "Recently, one group showed that BRAF MTs altered the tumor microenvironment by regulating the MAPK pathway, and MAPK activation is involved in NRF2 nuclear translocation." (PMID 34069882, 2021). "Subsequently, one of the six patients in the study had notable tumour progression upon discontinuing the BRAF inhibitor." (PMID 33557011, 2021). "These are diagnosed at early stages, and tumor growth is stepwise and encompasses mutations in KRAS, BRAF, PIK3CA, and PTEN." (PMID 34721577, 2021). "Of patients with known BRAF V600E based on the ddPCR tumor assay, 4/5 had MAF above the LOQ, ranging from 0.286–4.544%." (PMID 33799709, 2021). "The presence of genetic alterations in tumor cells, such as EGFR and BRAF gene mutations, as well as ALK and ROS1 gene rearrangements, are indications for targeted therapies." (PMID 33921237, 2021). "The SEER-Medicare linked database lacks information on the status of tumor mutations, including KRAS and NRAS (biomarkers of exclusion from anti-EGFR therapy), and BRAF (biomarker of poor prognosis)." (PMID 34910154, 2021). "Fifteen patients with BRAFV600E mCRC were treated with vemurafenib (BRAF inhibitor) and panitumumab, and 10 of 12 evaluable patients showed some tumor regression with two patients showing a partial response and stable disease lasting more than 6 months." (PMID 34299337, 2021). "Currently, the heterogeneity of the BRAF-V600E status of the primary tumor and metastases, concordance, and tissue coincidence are widely studied." (PMID 34319022, 2021). "Patient and tumor characteristics associated with OS after BM diagnosis were age, site of primary tumor, ECOG PS, BRAF status, site of BMs, number of BMs and lung metastases in univariate analysis." (PMID 34733283, 2021). "A tumor analysis, i.e., MSI/dMMR status +/− BRAF mutational/MLH1 methylation status, is of great importance to identify the patients who should benefit from MMR germline genetic testing." (PMID 33530449, 2021). "We conclude that mutant KRAS and BRAF impact the intrinsic sensitivity of tumor cells to chemotherapy and targeted therapy." (PMID 34771595, 2021). "Sato, in a recent study on 22 cases of PTC, concluded that BRAF V600E, when detected in pre-surgery plasma is indicative of a high fraction of BRAF V600E in the tumor, and extrathyroidal extension." (PMID 35008368, 2021).
tumor (continued). "Dynamic rewiring of signaling networks allows tumor cells to adapt to the BRAF and MEK inhibitors treatment." (PMID 34304249, 2021). "After progression, patients with RAS/BRAF WT tumor according to liquid biopsy will continue EGFR blockade while changing chemotherapy backbone (FOLFOX)." (PMID 33920531, 2021). "Although this cohort was modest in size, BRAF-mutant GBM constituted a unique subgroup with potential implications for tumor biology and treatment." (PMID 34625582, 2021). "For example, cancers harboring translocations that form fusion transcripts, such as BCR-ABL, or mutations, such as BRAF or EGFR, depend on these gene products’ activity for tumor maintenance." (PMID 34211974, 2021). "We analyzed prognostic factors in 148 patients with SNADETs, focusing on TNM stage, the anatomical location of the tumor, KRAS mutation, BRAF mutation, Fn, mucin phenotype, and PD-L1 status." (PMID 34797780, 2021). "Combined OR suggested that SMAD4 gene mutation has nothing to do with age, gender, tumor grade, MSI or BRAF status." (PMID 34301194, 2021). "These combinatory therapies are important, as HGF/c-Met signaling has been implicated in the conferral of resistance to BRAF and MEK inhibitors, and c-Met inhibitors hold promise as potential additions to these therapies to promote tumor regression." (PMID 33807778, 2021). "Considering that patients who have the BRAFV600E mutation maintain disease progression or rapidly develop resistance upon treatment with BRAF inhibitors, at least a proportion of cells within the tumour maintain intrinsic resistance mechanisms." (PMID 34066022, 2021). "On the contrary, other genes in the list (i.e., PIK3CA, PTEN, BRAF) are well-known tumor suppressor genes or oncogenes in many cancers." (PMID 34768773, 2021). "Complete and partial responses to BRAF inhibition have also been observed in patients with complete loss of PTEN tumor expression and with PIK3CA tumor-associated activating mutations." (PMID 34680615, 2021). "BRAF alterations have been shown to be mutually exclusive with KRAS mutations, and represent another potential therapeutic target in KRAS wild-type tumours." (PMID 34956889, 2021). "In the small PTC group, BRAF V600E tumours had a significantly greater occurrence of lymph node metastases (p = 0.0016), tall cell variants (p = 0.0011), and greater than one aggressive feature (p = 0.0034)." (PMID 34742355, 2021). "Whereas BRAF/MEK inhibitors drive NKX2-1-positive tumor cells into quiescence, NKX2-1-negative cells fail to exit the cell cycle after the same therapy." (PMID 33821796, 2021). "Outcomes following local treatment were analyzed for primary tumor sidedness of CRC, RAS, and BRAF mutations and MSI status." (PMID 34440165, 2021). "A multicenter analysis focusing on acquired BRAFi resistance reported that 13% of the examined patient cohort had increasing BRAF gene copy number during tumor progression compared to the CNA status of the gene at the time of diagnosis." (PMID 34885093, 2021). "For BRAF, a differential pattern was observed only in the proneural subtype, being upregulated in tumours from young patients and downregulated in elderly patients." (PMID 34123356, 2021). "The calculated frequency of tumor-initiating BRAF KO cells (TIC) was only 4–5-fold lower than that of BRAF intact controls." (PMID 33674596, 2021). "Some CRC cells produce abnormal BRAF proteins that promote tumour growth, hence being an important therapeutic target." (PMID 34440099, 2021). "It has been observed that enhanced activity of mutant TERT, which acts as an oncoprotein, accelerates further progression of cancer cells and tumor development, especially when BRAF V600E is already present." (PMID 34769260, 2021).
tumor (continued). "In preclinical trials, anti-CCL2 in combination with BRAF-targeted therapy reduced tumour sizes, as did anti-CXCR4 peptides when used alongside PD-1, and both demonstrated a reduction in MDSCs and T-regs." (PMID 34830780, 2021). "The B-Raf proto-oncogene serine/threonine kinase (BRAF) mutation is involved in the pathogenesis of PTC and is related to tumor progression, recurrence, and mortality." (PMID 34069887, 2021). "By contrast, BA tumours develop in the proximal/right colon and carry a Wnt-low, foetal-like signature which correlates with BRAF-mutant status, right-sidedness, MSI-high, CMS1 CRCs as well as pre-neoplastic SSAs in humans." (PMID 34103493, 2021). "Sorafenib is a multi-kinase inhibitor against VEGFR-1, VEGFR-2, VEGFR-3, BRAF, and c-Kit that downregulates both angiogenesis and tumor proliferation in multiple cancer cell lines." (PMID 33807778, 2021). "We finally took advantage of an additional in vitro model closer to the actual human tumor: a BRAF-mutant patient-derived organoid (PDO) named CRC0079." (PMID 34359705, 2021). "Vemurafenib (720 mg for 28 days, as an off-label drug) was first tested on a 12-year-old Caucasian boy with a right frontoparietal GBM (BRAF V600E) treated with conventional modalities, who developed tumour recurrence 2.5 years from diagnosis." (PMID 33557011, 2021). "BRAF participates in the pathological mechanism of 7% of human neoplasms, especially in patients with melanoma and colorectal, thyroid, and lung cancer." (PMID 33980169, 2021). "Specifically, Twist1 was found to correlate with the thyroid differentiation score (TDS) and to associate with the histological variants, BRAF/RAS phenotype, tumor size, lymph node metastasis, and TNM stage." (PMID 34575184, 2021). "On average, tumour mutational burden (TMB) was 18 mutations/Mb and 34.4%, 31.3% and 25.7% of patients had structural or copy number mutations in KRAS, BRAF and NRAS, respectively." (PMID 34600575, 2021). "Genomic testing revealed increased tumor mutational burden and alterations in NF1, BRAF, CDKN2A/B, TERT." (PMID 34926265, 2021). "Tumor progression after initial CR to BRAF ± MEKi therapy was found in 22/37 patients and was most common in patients who had to discontinue TT in the course of the disease." (PMID 34065877, 2021). "This showed positivity for the following mutations: BRAF V600E, PTEN Exon 9, PDL1-2+, and a high tumor mutation burden." (PMID 34503234, 2021). "Another study found that endothelin receptor antagonists suppressed high AXL tumor populations and re-sensitized cells to BRAF inhibitors." (PMID 35008286, 2021). "We posit that CCT3833 inhibits tumor growth in RAS-mutant models through on-target inhibition of BRAF and CRAF, and additional on-target inhibition of SRC." (PMID 33130216, 2021). "For instance, lncRNA SATB2-AS1 was found to be up-regulated when BRAF mutation occurs in RCC in our study, and it was recently reported to inhibit tumor metastasis and affect tumor immunity in CC, indicating that BRAF plays a crucial role in TIME." (PMID 34211853, 2021). "As in the metastatic setting, these data argue against employing Wnt inhibitors for APC-deficient tumours, but advocate their use for BRAF/KRAS-mutated serrated tumours that lack APC mutation (encompassing subsets of CMS1, CMS3, and CMS4 tumours)." (PMID 33673710, 2021). "BRAF V600E mutation is a marker of tumor aggressiveness, and is associated with poorer prognosis in CRC at the localized or metastatic stage than in BRAF wild-type." (PMID 34063682, 2021). "The genomic scoring system BRS (BRAF-RAS score) was developed to quantify the extent to which a tumor’s expression profile resembles a BRAFV600E or RAS-mutant neoplasm." (PMID 33299111, 2021). "Using this BA signature to interrogate CRC-patient datasets, we identified a significant correlation with BRAF mutation, right-sidedness, and the CMS1 subtype in CRC-patient tumours." (PMID 34103493, 2021).
tumor (continued). "MAPK pathway genes (BRAF, NRAS, and NF1) were frequently mutated throughout all tumor regions (truncal mutations)." (PMID 33535416, 2021). "A patient with BRAF V600E mutation and PD-L1 positive who relapsed from PTC to advanced ATC was treated with vemurafenib combined with nivolumab, and the tumor subsided significantly." (PMID 34266418, 2021). "Patients experiencing tumor progression with BRAF genetic alteration as an ARM to osimertinib in EGFR-mutant NSCLC usually receive platinum-based chemotherapy." (PMID 34575554, 2021). "Fresh frozen tumor tissue or FFPE slides were available for testing for all patients (n = 5 BRAF V600E, n = 3 fresh frozen tissue, n = 2 FFPE slides; n = 4 BRAF WT fresh frozen tissue)." (PMID 33799709, 2021). "To investigate tumor‐derived cfDNA using sensitive and validated PCR‐based assays, we focused on the detection of KRAS and BRAF mutations." (PMID 33635598, 2021). "Surprisingly, Nkx2-1 deletion in both the concomitant and sequential tumor models led to increased MAPK signaling downstream of oncogenic BRAF as assessed by IHC." (PMID 33821796, 2021). "While BRAF is a key driver in these tumor types, it is now well established that BRAF signaling plays an important role in immunosuppression." (PMID 34439194, 2021). "PI3K inhibitors acted on tumor cells that were resistant to BRAF inhibitors and resulted in a decrease in PD-L1 expression." (PMID 34422625, 2021). "While mutant BRAF-driven serrated tumours show a clear predilection for the right side of the colon in humans, most existing mouse models develop lesions primarily in the small intestine rather than the colon." (PMID 34103493, 2021). "While BRAF inhibition can result in favorable changes in the tumor immune microenvironment due to tumor intrinsic effects, these inhibitors also have direct effects on lymphocytes and other immune cells." (PMID 34025662, 2021). "Specific comparison of EGFR, KRAS and BRAF findings were compared following the analysis of tumor tissue, PB cfDNA, MPE cell pellets (cell-blocks) and cell-free MPE samples from the same probands." (PMID 34257581, 2021). "RET fusions were observed in a small fraction (<1%) of metastatic CRC (mCRC), where their presence was associated with old age, right‐sided tumor origin, wild‐type RAS and BRAF, microsatellite instability (MSI)‐high tumors, and poor prognosis." (PMID 34741450, 2021). "Initially, BRAF-i were used as monotherapy, allowing dramatic response in terms of reduction of tumor size." (PMID 35008245, 2021). "Compared to BRAF V600E mCRC, BRAF non-V600 mCRC were more frequently left-sided, had a lower tumor burden and displayed a lower grade and an MMR proficient/MSS status." (PMID 33925278, 2021). "High-grade skin toxicity, together to the circulating tumor DNA RAS/BRAF/EGFR wild-type status were the only variables with an impact on PFS and OS." (PMID 34830870, 2021). "The common variations include loses in 22q (includes NF2 and CHEK2) and 10q, and gains in 1q and oncogenic drivers BRAF (in BRAF wild-type tumours) and TERT." (PMID 34062862, 2021). "We established novel canine TCC cell lines from two tumor tissues and one metastatic lymph node of canine TCC patients harboring the BRAF V595E mutation." (PMID 34502061, 2021). "That is why tumor-plasma concordance of non-BRAF mutations in our study was rather low (28%) and it concerned only variants with VAF in tumor samples higher than 30%." (PMID 34356096, 2021). "In summary, the small molecules induced degradation of BTK, CDK4/6, BCR-ABL and BRAF in cancer cells had a better anti-tumor cell proliferation effect than simply inhibiting, and they also demonstrated promising power in overcoming tumor drug resistance." (PMID 34249939, 2021). "In this study, we identified a correlation between the pathological tumor diameter and the MAF, but it was difficult to predict recurrence by measuring cfDNA with BRAF V600E mutation in the perioperative period of radical resection of CRC." (PMID 34168268, 2021).